ATM (ATM serine/threonine kinase)
Diseases named in the same sentence as ATM in open-access papers (continued):
Sharing a sentence is not in itself a finding about the gene and the disease.
cancer (continued). "Collectively, our findings supports the hypothesis that activation of the ATM/AKT/GSK-3β signaling pathway leading to CDK4/CDK6/cyclin D1 overexpression plays a key role in LDR-induced hormesis, and is responsible for the difference of hormesis induced by LDR in normal and cancer cells." (PMID 27708248, 2016). "The identification of ATM as a positive modulator of several signalling networks that sustain tumorigenesis, including oxidative stress, hypoxia, receptor tyrosine kinase and AKT serine-threonine kinase activation, raise the question of whether ATM function in cancer may be more complex." (PMID 24681585, 2014). "Second, although several factors have been known to determine cancer cell response to ionizing radiation, we observed that the main intrinsic determinant of differential radiosensitivity was DNA repair capacity, in particular ATM level, rather than cell cycle status or antioxidant levels." (PMID 23185620, 2012). "We recently proposed that metformin, by activating an ATM-mediated DDR, may function as a “tissue sweeper” that significantly decreases the accumulation of dysfunctional, pre-malignant cells, including those with the ability to initiate and propagate tumors (i.e., cancer stem cells)." (PMID 22837425, 2012). "It remains to be elucidated, however, whether metformin's ability to strongly activate the ATM/Chk2-regulated DDR checkpoint is a critical event that prevents neoplastic epithelium to progress unimpeded into invasive cancer in individuals without type 2 diabetes." (PMID 22203527, 2011). "When analyzed as continuous variable, HRD score in cancers with BRCA2 and ATM alterations was significantly higher than in those without identified HRR mutations." (PMID 41465280, 2025). "We find that regardless of the cell replication error status, both ATM and ATR inhibitors exert preferential growth inhibitory effects on acid-exposed cancer cells." (PMID 38366255, 2024). "Although BRCA1/2 is the most common genetic variant detected on germline testing, it is prudent to recognise non-BRCA HRR-related genes such as PALB2, ATM and RAD51 can also contribute to HBOC and other carcinomas." (PMID 39796639, 2024). "This study reports that NLRP3 is down-regulated in cancers and identifies a novel non-immune function for NLRP3 in maintaining genome integrity through the control of ATM activation in response to DSB." (PMID 36746533, 2023). "This group included 66 (22.7%) with a known PDAC PGV (54 BRCA2, 5 PALB2, 5 ATM, 2 BRCA1) previously identified outside the MDPC on the basis of personal or family history of other cancer diagnoses, but no known PDAC family history." (PMID 35906821, 2022). "Despite being elevated in a subset of cancer samples, NBS1 overexpression is not likely to be important for ATM activation, which suggests that additional layers of regulation exist for NBS1-mediated ATM activation." (PMID 32203529, 2020).
cancer (continued). "Thus, with OS seemingly poor in multiple cancer types with ATM alterations regardless of immunotherapy or platinum‐based treatment, one could assume that patients with tumors harboring ATM alterations would need a novel therapeutic approach for improving outcomes." (PMID 33098265, 2020). "Among the signalling pathways discovered included the DNA repair and Androgen and ATM signalling pathways for TNBC and the DNA damage response, molecular mechanisms of cancer, and ATM and GP6 signalling pathways for non-TNBC." (PMID 32724790, 2020). "Three tumor suppresser genes, including CYLD, ATM, and TSPYL2, showed a negative correlation with UBE2C in several cancers with a similar moderate to strong negative correlation for them in the following cancers: LUSC, READ, UCEC, OV, and UCS." (PMID 31067633, 2019). "Although three additional ATM rare truncations were found in BRCA and GBM in the validation cohort, no events were detected in LUAD and PRAD, two cancer types with significant results in the discovery cohort." (PMID 26689913, 2015). "Moreover, there was no significant change in the levels of ATM, BCL-2, and TP-53 genes, but there were BAX (≈0.8 fold) genes significantly up-regulated when compared the negative control in HT-29 cancer cell lines." (PMID 40872562, 2025). "Furthermore, Salmonella typhi isolates presented high resistance rates in cancer patients compared to noncancer patients at COL (69.23% versus 0.00%), NIT (76.92% versus 0.00%), ATM (53.82% versus 20.00%), and CXM (100% versus 60.00%)." (PMID 39036470, 2024). "The epigenetic signatures of ATM, BRCA1, PALB2, RAD51B, and XRCC3 have also been explored in MBC (32.4% with germline BRCA2 PV) in matched normal and gynecomastia tissue samples (obtained from patients without cancer or a family history of BC)." (PMID 34298749, 2021). "In cancer, NK cell senescence has not been clearly defined, but NK cells do release SASP-like molecules in response to tumor cells, and upregulate KLRG1 and ATM phosphorylation, key senescence markers, in response to chronic stimulation." (PMID 33120910, 2020). "Thus, one possible explanation for the absence of cancer in C9orf72-ALS is the retention of functional homologous recombination and ATM-mediated cell cycle checkpoint, akin to RIDDLE." (PMID 29584802, 2018). "Although RAP80 is a substrate of ATM and is also involved in G2/M checkpoint control in response to DNA damage, whether RAP80 plays a reversed regulation on ATM activity in unstressed cancer cells has not been explored." (PMID 29396516, 2018). "However, we found that both baicalein and baicalin did not induce significant activation and phosphorylation of ATM in HCT116 and SW480 cancer cells." (PMID 29732005, 2018). "The first ATM inhibitor, utilised in in vivo studies was KU59403 (KuDOS Pharmaceuticals, now AstraZeneca, UK), and although it was not cytotoxic to human cancer cell lines, it significantly increased the cytotoxicity of topoisomerase I and II agents: camptothecin, etoposide and doxorubicin." (PMID 29069866, 2017).
cancer (continued). "Accordingly, we have shown that SMOX overexpression further enhances the DNA-PKCs and ATM phosphorylation/activation status induced by IR in FN-RMS cells 3 h post-irradiation, a time interval commonly known to be sufficient for DNA repair in normal but not in cancer cells." (PMID 36755974, 2023). "It has been shown that ATM and ATR regulate partially overlapped but nonredundant downstream pathways during DNA repair, and defects in one PIKK protein might be compensated by the other to maintain the survival of cancer cells." (PMID 38041093, 2023). "In SCLC, it can be observed that cancer gene alterations appear to be more frequent in women, the most consistent differences being observed in PTRD, CREBBP, GRM3, ATRX, NOTCH3, and PDE4DIP, while ATM appears to be altered in 5.26% of men, and no alterations were depicted in women." (PMID 35330454, 2022). "To date, the complete spectrum of the interplay between ATM, DNA-PKcs and ATR, has not been fully uncovered, but could provide a better understanding of the synthetic lethality and of the synergistic effects of ATMi, DNA-PKcsi and ATRi in cancer therapy." (PMID 32015826, 2020). "Importantly, ATM plays non-nuclear functions in addition to the DDR signalling that may contribute to its dual, opposing role in cancer." (PMID 28423511, 2017). "Moreover, DNA damage proteins and cancer cells have specific properties, including cancer-specific DDR defects and lack of G1 checkpoint control, that may highlight particular vulnerabilities of the cancer, supporting PARP, ATR, ATM, CHK1/2, and WEE1 as therapeutic targets." (PMID 34930377, 2021).
tumor (1,314 papers, 2003 to 2026). "DNA sequencing analysis with matched germline whole-exome sequencing identified a pathogenic ATM mutation, with biallelic ATM deficiency in tumor." (PMID 41878701, 2026). "Genetic analysis identified the presence of ATM nonsense mutation and heterozygous deletion in the tumor specimen." (PMID 40796116, 2025). "Exploratory aims assess the influence of uridine 5′-diphospho-glucuronosyltransferase family 1 member A1 (UGT1A1), tumor mutation profiles, and ATM expression on treatment response and toxicity." (PMID 40869030, 2025). "Alterations in ATM expression often manifest as an ultra-high tumor mutational burden, which is associated with a better response to immunotherapies." (PMID 40144209, 2025). "Mutations or downregulation of ATM have been linked to increased sensitivity to radiation-induced cell death and tumor progression." (PMID 40652278, 2025). "Next, we evaluated the association between ATM genotypes and irradiated tumor progression among 168 patients with ATM missense mutations who received RT to 343 lesions." (PMID 40570257, 2025). "Mutational signature analysis using the SIGNAL Ovary signature set33 was performed for tumours with demonstrable loss or inactivation of the wildtype allele in multiple samples (three PALB2 and ATM tumours each)." (PMID 39794353, 2025). "A loss of ATM function can also affect the expression of molecules on tumor cells that are involved in interactions with immune cells." (PMID 40310425, 2025). "In either case, it would be of interest to explore MSI-H tumours as a potential enrichment for ATM deficiency." (PMID 40382524, 2025). "It has been shown that mutated ATM expression is high in CRC tumours and serves as one of the biomarkers in CRC." (PMID 40806481, 2025). "Overall, BAY-1895344 exhibits compelling anti-tumour efficacy, particularly in solid malignancies with ATM pathway deficiencies." (PMID 40256842, 2025). "Conversely, ATM positivity was associated with improved disease-free survival, supporting its function as a tumor suppressor via DNA repair." (PMID 40869030, 2025). "Animal studies have shown that ATM deficiency delays tumor growth and sensitizes tumors to PD-1 blockade and radiotherapy." (PMID 40825766, 2025). "The critical role of ATM lies in preserving genomic integrity by preventing DNA mutations that contribute to tumor formation and progression." (PMID 40310425, 2025). "Elevated ATM expression has been observed in OvCa tumours and is associated with poor patient survival." (PMID 41008855, 2025). "Given the higher genomic instability caused by ATM dysfunction, an indirect impact on the immune system or tumor microenvironment potentially influencing the efficacy of CAR T-cell therapy can be anticipated." (PMID 41023839, 2025). "It was worth noting that only some samples in Subtype 1 appeared mutation of ATM, a tumor suppressor functioning in cell cycle checkpoint." (PMID 39972282, 2025).
tumor (continued). "Carriers of heterozygous pathogenic variants in the ATM gene have an increased risk of neoplasms incidence, mostly breast but also of OC with an absolute estimated risk of 2–3 times greater than the general population." (PMID 39984762, 2025). "ATM loss increases tumor sensitivity to radiotherapy via radiosensitization of neoplastic cells rather than the vasculature." (PMID 40244686, 2025). "The TERT promoter and ATM mutations further contribute to the aggressive cytologic features of the tumor." (PMID 40125165, 2025). "This suggests that the inhibitory effect of ATM deficiency on tumor growth is dependent on the soundness of the immune system." (PMID 40825766, 2025). "Future studies should focus on larger cohorts and more comprehensive tumor analyses to further clarify the role of ATM mutations in MM development." (PMID 41331641, 2025). "In CRC, the DDR gene, ataxia telangiectasia mutated (ATM), is one of the most commonly found mutated tumour suppressor genes." (PMID 40806481, 2025). "Olaparib, a PARPi, has been found to shrink the tumour size in the ATM deficient cell lines SK-CO-1 and HCT116." (PMID 40806481, 2025). "In summary, PALB2 and ATM were the only proposed genes displaying consistent, verifiable somatic biallelic inactivation across multiple tumour samples from germline variant carriers." (PMID 39794353, 2025). "Two tumours harboured a private non-synonymous mutation in the HR-DDR pathway genes ATM and BARD1, respectively." (PMID 39020404, 2024). "Based on the large number of variants and VUS in ClinVar, the Ataxia Telangiectasia mutated (ATM) tumor suppressor gene was selected for initial work of this VCEP." (PMID 38854136, 2024). "Though the patient did not meet contemporaneous NCCN criteria for genetic testing based on her family history, she was referred for follow‐up genetic counseling and testing due to her ATM mutation detected on tumor CGP." (PMID 38898688, 2024). "In preclinical models, ATRi kills tumor cells with loss of ataxia telangiectasia mutated (ATM), AT-rich interactive domain-containing protein 1A (ARID1A), and specific components of the DDR pathway or those driven by oncogenes such as cyclin E and Myc." (PMID 37934611, 2024). "Niraparib also caused significant tumor regression in one-third of the NSCLC PDX models harboring deleterious biallelic ATM mutations." (PMID 38807759, 2024). "To test this, we analyzed genomes from a diversity of tumor types with driver mutations in either ATM, MEN1, SETD2, BRCA1, BRCA2 and ATRX." (PMID 38909016, 2024). "After IFN-γ stimulation and radiation, the expression of MHC class I was upregulated in the two cell lines, especially in ATM-deficient tumor cell lines." (PMID 39033176, 2024).